CLDN19 (claudin 19)
Description:
Forms paracellular channels: coassembles with CLDN16 into tight junction strands with cation-selective channels through the strands, conveying epithelial permeability in a process known as paracellular tight junction permeability. Involved in the maintenance of ion gradients along the nephron. In the thick ascending limb (TAL) of Henle's loop, facilitates sodium paracellular permeability from the interstitial compartment to the lumen, contributing to the lumen-positive transepithelial potential that drives paracellular magnesium and calcium reabsorption (By similarity). Forms paracellular barriers on its own. In the peripheral nervous system, represents a major constituent of the tight junctions in Schwann cells and contributes to electrical sealing. During retinal neurogenesis, may regulate the barrier properties of tight junctions in retinal pigment epithelium, required for proper retinal tissue differentiation and vision (By similarity).
Synonyms: HOMG5
Tractability: Antibody: UniProt places it where antibodies can reach, with high confidence; its Gene Ontology location is reachable by antibodies, with high confidence; UniProt predicts a signal peptide or a membrane-spanning region; the Human Protein Atlas places it where antibodies can reach.
Gene: Protein-coding gene on chromosome 1 (42,733,093 to 42,740,254, reverse strand). Ensembl gene ENSG00000164007.
Subcellular location: Cell junction, tight junction; Cell membrane
Subcellular location (Human Protein Atlas): Plasma membrane
Pathways (Reactome):
Cell-Cell communication: Tight junction interactions
Gene Ontology:
Molecular function: cell-cell adhesion mediator activity; paracellular tight junction channel activity; protein binding; identical protein binding; structural molecule activity
Biological process: actin cytoskeleton organization; cell junction assembly; negative regulation of cell migration; negative regulation of cell population proliferation; negative regulation of gene expression; paracellular transport; positive regulation of gene expression; regulation of transepithelial transport; retinal pigment epithelium development; apical junction assembly; calcium-independent cell-cell adhesion; renal absorption; tight junction organization
Cellular component: apical junction complex; basolateral plasma membrane; bicellular tight junction; perinuclear region of cytoplasm; plasma membrane; tight junction; cell junction; cytoplasm; membrane; mesaxon; nucleus; paranodal junction; Schmidt-Lanterman incisure
Genetic constraint (gnomAD): Loss-of-function variants: 18 observed, 21.28 expected, observed/expected ratio (o/e) 0.85, 90% interval 0.58 to 1.25. The upper end of that interval is the gene's LOEUF score, 1.25, which puts it in group 5 of 6, group 1 being the genes least tolerant of losing a copy. Missense variants: 243 observed, 271.21 expected, observed/expected ratio (o/e) 0.9, 90% interval 0.81 to 1. Synonymous variants: 114 observed, 119.89 expected, observed/expected ratio (o/e) 0.95, 90% interval 0.82 to 1.11.
Homologues: Orthologues: macaque CLDN19 (100% identical), chimpanzee CLDN19 (99% identical), rabbit CLDN19 (98% identical), pig CLDN19 (96% identical), dog CLDN19 (95% identical), guinea pig CLDN19 (95% identical), rat Cldn19 (95% identical), mouse Cldn19 (90% identical), tropical clawed frog cldn19 (74% identical), zebrafish cldn19 (63% identical). Paralogues in human: CLDN1 (54% identical), CLDN7 (50% identical), CLDN3 (42% identical), CLDN9 (42% identical), CLDN14 (42% identical), CLDN4 (40% identical), CLDN6 (39% identical), CLDN2 (38% identical), CLDN5 (38% identical), CLDN17 (37% identical), CLDN8 (34% identical), CLDN15 (34% identical), and 10 more.
Diseases named in the same sentence as CLDN19 in open-access papers:
CLDN19 is named in the same sentence as 34 diseases in open-access papers, as found by Europe PMC text mining. Sharing a sentence is not in itself a finding about the gene and the disease. The quoted sentences say what the papers report.
Hypercalciuria (23 papers, 2013 to 2025). "Biallelic loss-of-function mutations in CLDN19 are known to cause familial hypomagnesemia with hypercalciuria and nephrocalcinosis." (PMID 40372791, 2025). "This physical coupling is highlighted by the fact that the loss of either claudin-16 or claudin-19 results in the same disease, familial hypomagnesemia with hypercalciuria and nephrocalcinosis." (PMID 34810264, 2021). "CLDN19 mutations cause recessively inherited familial hypomagnesemia with hypercalciuria and nephrocalcinosis (FHHNC)." (PMID 34576252, 2021). "So far, 3 claudins (10b, 16 and 19) have been causally traced to rare human syndromes: variants of CLDN10b cause HELIX syndrome and variants of CLDN16 or CLDN19 cause familial hypomagnesemia with hypercalciuria and nephrocalcinosis." (PMID 32164158, 2020). "Mutations in CLDN16 and CLDN19, which encode the tight junction proteins claudin-16 and claudin-19 respectively, give rise to the condition familial hypomagnesaemia with hypercalciuria and nephrocalcinosis (FHHNC)." (PMID 31935940, 2020). "Mutations of claudin-19 cause Familial Hypomagnesaemia and Hypercalciuria, Nephrocalcinosis with Ocular Involvement." (PMID 30937396, 2019). "Familial hypomagnesemia with hypercalciuria and nephrocalcinosis (FHHNC) is a rare autosomal-recessive disorder caused by mutations in either CLDN16 or CLDN19 genes." (PMID 30305086, 2018). "Mutations in the claudin genes, claudin-16 and claudin-19, cause familial hypomagnesemia with hypercalciuria and nephrocalcinosis (FHHNC)." (PMID 23799361, 2013). "FHHNC patients and animal models with claudin-16 or claudin-19 mutations are known to have hypercalciuria, nephrocalcinosis, and nephrolithiasis." (PMID 23799361, 2013). "CLDN16, encoding claudin-16/paracellin-1, and CLDN19, encoding claudin-19, are mutated in recessive familial hypomagnesemia with hypercalciuria and nephrocalcinosis." (PMID 24339795, 2013). "Conversely, Cldn19’s function may align with previous mutation studies on familial hypomagnesemia with hypercalciuria and nephrocalcinosis." (PMID 41171911, 2025). "Mutations in Cldn16 or Cldn19 that encode claudin-16 and claudin-19, respectively, cause familial hypomagnesemia with hypercalciuria and nephrocalcinosis (FHHNC) (OMIM: 248250), which is an autosomal-recessive renal tubular disorder which sees nephrocalcinosis as a main symptom." (PMID 38339056, 2024). "Renal hypomagnesemia 5 with ocular involvement (OMIM phenotype number 248190) is an AR condition due to inactivating variants in CLDN19, resulting reduced reabsorption of calcium (hypercalciuria) and magnesium (hypermagnesuria)with hypomagnesemia, visual impairment, NC, NL, and progressive CKD." (PMID 38606357, 2024). "Paracellular Ca2+ reabsorption is better characterized in the thick ascending limb, in which claudin-16 and claudin-19 form Ca2+ permeable pores and mutations in these genes cause the syndrome familial hypomagnesemia with hypercalciuria and nephrocalcinosis associated with severe renal Ca2+ wasting." (PMID 34810264, 2021). "We also evaluated the expression of Cldn16 and Cldn19, since their crucial role in ameloblast tight-junction formation has been recently indicated; their mutation causing familial hypomagnesaemia with hypercalciuria and nephrocalcinosis and amelogenesis imperfecta." (PMID 29375389, 2017). "Familial hypomagnesemia with hypercalciuria and nephrocalcinosis (FHHNC) is a rare autosomal recessive renal tubular disorder caused by mutations in the CLDN16 or CLDN19 genes." (PMID 40826740, 2025). "Human CLDN16 and CLDN19 variants are associated with familial hypomagnesemia with hypercalciuria (FHHNC; OMIN 248250), and a missense variant in CLDN19 has been associated with NTDs." (PMID 37377737, 2023). "For example, mutations in six of the amelogenesis imperfecta-associated genes (CLDN16, CLDN19, FAM20A, KCNJ1, SLC4A1, and WDR72) are associated with nephrocalcinosis, hypercalciuria, and renal failure." (PMID 33672174, 2021).
Hypercalciuria (continued). "Familial hypomagnesemia with hypercalciuria and nephrocalcinosis is an autosomal recessive disorder caused by variants of the CLDN16 (OMIM #248250) and CLDN19 (OMIM #248190) genes." (PMID 32164158, 2020). "Familial hypomagnesemia with hypercalciuria and nephrocalcinosis (FHHNC) is an ultra-rare autosomal recessive renal tubular disease with an incidence of less than 1 in 1,000,000 individuals, caused by loss-of-function mutations in CLDN16 and CLDN19." (PMID 40173198, 2025). "Familial hypomagnesemia with hypercalciuria and nephrocalcinosis (FHHNC) is an ultra-rare autosomal recessive renal tubular disease with an incidence of <1/1.000.000 individuals, caused by loss-of-function mutations in CLDN16 and CLDN19." (PMID 40173198, 2025).
nephrocalcinosis (21 papers, 2013 to 2025). Nephrocalcinosis is a disorder that occurs when too much calcium is deposited in the kidneys. "Nephrocalcinosis is often caused by defects in renal epithelial transport including mutations in Cldn16, Cldn19, Clcn5 and Slc34A1." (PMID 38339056, 2024).
amelogenesis imperfecta (4 papers, 2020 to 2022). Amelogenesis imperfecta (AI) represents a group of developmental conditions affecting the structure and clinical appearance of the enamel of all or nearly all the teeth in a more or less equal manner, and which may be associated with morphologic or biochemical changes elsewhere in the body. "Mutations in CLDN19 are associated with amelogenesis imperfecta, a genetic disorder characterized by tooth enamel defects." (PMID 36523561, 2022). "Cldn16 and Cldn19 are also expressed in ameloblast tight junction and loss-of-function mutations of CLDN16 and CLDN19 genes are associated with amelogenesis imperfecta." (PMID 32164158, 2020). "Mutations in CLDN10, CLDN16, and CLDN19 are associated with amelogenesis imperfecta in humans and in mice, deletion of Cldn3 significantly reduces the enamel volume compared to that of wild-type mice." (PMID 33195274, 2020). "Cldn3 knockout mice exhibit enamel defects caused by excess accumulation of extracellular matrix proteins in the forming enamel and mutations in CLDN19 are associated with Amelogenesis Imperfecta, a genetic disorder characterized by tooth enamel defects." (PMID 32760237, 2020).
diabetes (3 papers, 2017 to 2022). "We, hereby, replicate the findings from previous studies on the effect of TRPM6, SLC41A2 and CLDN19 on diabetes risk." (PMID 28224192, 2017). "CLDN19 was found to associate with diabetes risk independently from serum magnesium levels." (PMID 28224192, 2017). "Therefore, a magnesium-independent role for CLDN19 in diabetes risk could be proposed since alterations in tight junctions have previously been linked with diabetes." (PMID 28224192, 2017). "Genetic variation in CLDN19, CNNM2, FXYD2, SLC41A2, and TRPM6 significantly influenced diabetes risk (p < 0.05), and for CNNM2, FXYD2, SLC41A2 and TRPM6 this risk was completely mediated by serum magnesium levels." (PMID 28224192, 2017). "Genetics seems to be a vital risk factor for Type 2 diabetes, and serum magnesium levels may modify the risk of diabetes through several magnesium-regulating genes such as TRPM6, CLDN19, SLC41A2, CNNM2, and FXYD2." (PMID 35565766, 2022). "Furthermore, common genetic variation in magnesium regulating genes TRPM6, CLDN19, SLC41A2, CNNM2 and FXYD2 significantly modify the risk of diabetes through serum magnesium levels." (PMID 28224192, 2017).
renal failure (3 papers, 2018 to 2023). "Patients with p.G20D homozygous mutation in CLDN19 gene exhibit different progression to kidney failure suggesting that beyond the pathogenic mutation itself, other molecular events are favoring disease progression." (PMID 30305086, 2018).
kidney stones (2 papers, 2019). "Besides CLDN16 and CLDN19, in 2009, a genome-wide association study on an Icelandic and Dutch population revealed that a CLDN14 variant (rs219780[C]) is associated with kidney stones too." (PMID 31694170, 2019).
chronic renal disease (1 paper, 2013). "Our data indicate that patients with CLDN19 mutations have a high risk of progression to chronic renal disease." (PMID 23301036, 2013). "Our clinical data indicate that FHHNC patients with CLDN19 mutations have a high risk of progression to chronic renal disease." (PMID 23301036, 2013).
genital warts (1 paper, 2021). "In addition, in terms of molecular targeted therapy prediction, our results show that the increased expression of AQP2 and CLDN19 is associated with the sensitivity to imiquimod, an imidazoline derivative commonly used to treat genital warts." (PMID 34422051, 2021).
peripheral nerve injury (1 paper, 2018). Injury to a peripheral nerve. "Western blots outcomes also suggested that protein expressions of claudin-10 and claudin-19 were down-regulated after peripheral nerve injury." (PMID 30425652, 2018).
retinal degeneration (1 paper, 2019). Degeneration of the retina. "The mice were transduced on P0 with mutant CLDN19 and given 9-cis-retinal on PN30 after retinal differentiation was complete, but retinal degeneration was partial." (PMID 30937396, 2019).
tumor (3 papers, 2016 to 2026). "Other studies have described that UBE2C, along with the other signaling molecules such as AURKA, EMT, GRIK3, CDK1, and claudin 19, activates the WNT/β-catenin signaling pathway, thus altering tumor biology." (PMID 39479352, 2024).
cancer (2 papers, 2021 to 2025). A tumor composed of atypical neoplastic, often pleomorphic cells that invade other tissues. "Claudin family genes (e.g., CLDN6, CLDN19) are also served as biomarkers and therapeutic targets across cancers." (PMID 41287033, 2025).
peripheral neuropathy (2 papers, 2019 to 2024). A disorder affecting the peripheral nervous system. "Cldn19 KO mice are fertile and vital, but show the phenotype of a peripheral neuropathy, causing mainly motor defects, but in 50%, nerve conduction deficits as well." (PMID 31906086, 2019). "Cldn19-deficient mice also exhibited symptoms of peripheral neuropathy." (PMID 39621665, 2024).
CLDN19 also shares sentences with these, for which no sentence is quoted: Hypomagnesemia (9 papers); genetic disorder (2); age-related macular degeneration (1); Astigmatism (1); Bartter syndrome type 3 (1); Bartter syndrome type 4 (1); breast carcinoma (1); central serous chorioretinopathy (1); COVID-19 (1); diabetic retinopathy (1); Gitelman syndrome (1); HELIX syndrome (1); myopia (1); osteogenesis imperfecta type 1 (1); renal disease (1); renal hypomagnesemia type 3 (1); renal tumors (1); retinitis pigmentosa (1); Sorsby fundus dystrophy (1); Strabismus (1); Type 2 diabetes (1).